LEP (leptin)
Diseases named in the same sentence as LEP in open-access papers (continued):
Sharing a sentence is not in itself a finding about the gene and the disease.
Obesity (continued). "This study aims to explore the combined role of ANGPTL3, 4, 8, omentin-1, leptin, TNF-α, and IL-6 molecules known for their roles in fat metabolism, obesity, and inflammation, yet whose connection to PCOS is still debated in the development of PCOS." (PMID 41341944, 2025). "In the face of obesity and the expansion of WAT, leptin is hypersecreted, generating central and peripheral resistance to its action." (PMID 40195898, 2025). "By lowering the expression of target genes, such as those involved in inflammation (e.g., adiponectin, (TNF-α), leptin, and TLR 4), obesity treatment leads to the prevention of NF-kB activation." (PMID 40242447, 2025). "There are several possible mechanisms for obesity in BBS, including abnormal cilia, insulin resistance, leptin dysregulation, and the leptin–melanocortin receptor pathway, affecting both central appetite control and energy expenditure." (PMID 40087798, 2025). "Appetite hormones such as ghrelin, leptin, GLP-1, and PYY, are some of the most important body hormones that regulate appetite and prevent more appetite-related diseases such as obesity and diabetes." (PMID 41370490, 2025). "Moreover, leptin enhances the intracellular activation of thyroid hormones in muscle, which increases energy expenditure and may influence metabolic balance, particularly in the context of overweight and obesity." (PMID 40648864, 2025). "Previous studies have shown that obesity and HFD feeding impair PVAT‐mediated vasodilation through increased oxidative stress or diminished levels of adiponectin, leptin, and H2S." (PMID 41420377, 2025). "Obesity increases VAT volume, which is the main source of leptin, which typically plays a key role in regulating appetite, energy homeostasis, and body weight." (PMID 41149623, 2025). "Leptin (LEP), the product of the obesity gene, plays a vital role in food intake regulation and fat decomposition." (PMID 40302672, 2025). "Nevertheless, in high-fat-diet (HFD) models, acetate, propionate, butyrate suppress obesity-related leptin overexpression through downregulation DNMT1/3a/3b, reducing leptin promoter methylation." (PMID 40740992, 2025). "Serum leptin (LEP), a satiety-regulating adipokine often elevated in HFD-induced obesity, was significantly decreased by 28.80% in the L-SLN group (p < 0.05) and 36.39% in the D-SLN group (p < 0.05)." (PMID 40508058, 2025). "Leptin and ghrelin levels were similar in the group of girls with obesity and PCOS and the control group with obesity alone." (PMID 40491594, 2025). "Previous studies have proposed several mechanisms linking obesity to PAH, including inflammation, oxidative stress, endothelial dysfunction, increased leptin levels, reduced adiponectin levels, and altered estrogen metabolism." (PMID 41322909, 2025). "Here’s how different pathways and mechanisms underlie the processes: Apoptosis of oligodendrocyte precursor cells in the medial eminence of the hypothalamus can induce leptin resistance in ARC GABAergic neurons, leading to obesity." (PMID 40130157, 2025). "Enhancing insulin and leptin signaling through the deletion of specific phosphatases like PTP1B and TCPTP in these neurons prevents diet-induced obesity by increasing energy expenditure and stimulating the browning of WAT." (PMID 40130157, 2025). "In conclusion, leptin levels were significantly lower in individuals with newly diagnosed youth-onset T2DM compared to those with NGT, despite a positive correlation with obesity markers." (PMID 40630340, 2025). "This inflammatory response increases the secretion of proinflammatory cytokines, including tumor necrosis factor (TNF), interleukin-6 (IL-6), and leptin, while levels of insulin-like growth factor-1 (IGF-1) typically decrease with age and obesity." (PMID 41156491, 2025). "In diet-induced obesity, microglial SOCS3 is elevated, but STAT3 activation in response to leptin is blunted, while NF-κB-driven inflammation persists, demonstrating selective resistance." (PMID 41516046, 2025).
Obesity (continued). "Obesity is connected to increased levels of proinflammatory cytokines, such as IL-6 and TNF-alpha, and adipokines like leptin, which are known to activate the trigeminovascular pathways that play a role in migraines." (PMID 41278056, 2025). "Serum Wnt5a, leptin, and TNF-α showed significantly higher levels in females with obesity than controls and a significant increase with higher classes of obesity." (PMID 39837875, 2025). "One proposed mechanism for leptin resistance involves matrix metalloproteinase-2 (MMP-2), a proteolytic enzyme that becomes activated in the hypothalamus during obesity." (PMID 41226331, 2025). "These offspring exhibited typical signs of MetS that accompany obesity, including elevated levels of fasting serum TC, TG, FFA, insulin, and leptin, as well as reduced sLepr compared to the control offspring." (PMID 39792613, 2025). "Furthermore, elevated leptin may contribute to the pathophysiology of obesity." (PMID 40393800, 2025). "Leptin, a key regulator of appetite and energy expenditure, influences vasoconstriction and SNS activation, linking obesity to hypertension." (PMID 40430185, 2025). "The marked elevation in leptin levels (from 48.60 ± 27.39 to 8623.55 ± 1779.44 pg/mL) in the HFD group suggests the development of leptin resistance, a common feature in obesity." (PMID 41226391, 2025). "Using CCJ12, in vivo effects on bodyweight, cholesterol, HDL, LDL, and triglycerides, leptin, adiponectin, sE-selectin, CRP, MCP-1 and TNF-alpha factors were studied in a high fat diet-induced obesity rodent model." (PMID 40770283, 2025). "Furthermore, BSFL-MCFAs reduced serum glucose and leptin levels, mitigated hypothalamic endoplasmic reticulum stress marker expression, and decreased serum alanine transaminase levels, indicating protective effects against obesity-related metabolic dysregulation." (PMID 40427263, 2025). "Dense stroma‐induced hypoxia stabilizes HIF‐1α and, in concert with obesity‐related cytokines (such as IL‐6, TNF‐α, and leptin), activates the JAK/STAT3 pathway, upregulates PD‐1/PD‐L1 expression, and suppresses antigen presentation." (PMID 41267926, 2025). "Leptin levels are significantly elevated in women with PCOS, particularly in those with obesity and metabolic syndrome." (PMID 40385768, 2025). "In obesity, chronic activation of the JAK-STAT3-SOCS3 signaling pathway by leptin and IL-6 has been described." (PMID 41007770, 2025). "The project will investigate the additive effects of Cognitive Training (CT) and Social Training (ST) on leptin sensitivity, compared to stand-alone Intensive Health Behaviour Treatment (IHBT) in children with obesity or overweight." (PMID 40607230, 2025). "Additionally, while the changes in thyroid function in patients with OSAHS and obesity may be related to factors such as oxidative stress, inflammatory factors, and leptin, the underlying mechanisms of these relationships have not yet been thoroughly explored." (PMID 40438137, 2025). "In contrast to leptin, circulating APN concentrations are reduced in obese individuals, which is a phenomenon hypothesized to play a pivotal role in the pathogenesis of atherosclerosis and cardiovascular diseases associated with obesity and the metabolic syndrome." (PMID 40692591, 2025). "Furthermore, the ob/ob mouse model’s inherent limitations due to leptin deficiency may not accurately represent human obesity." (PMID 41228394, 2025). "GDM and obesity are multifactorial conditions influenced by various biochemical and molecular factors, such as apelin, VEGF, leptin, and DNA methylation." (PMID 41302116, 2025). "Therefore, leptin resistance might be considered the molecular bridge between metabolic dysregulation and cognitive dysfunctions due to hippocampal abnormalities, particularly memory, often seen in obesity." (PMID 40607230, 2025).
Obesity (continued). "In the context of obesity and T2DM, ACE2 deletion or Mas deletion leads to increased visceral adipose tissue, higher leptin levels, larger adipocyte size, and upregulated lipogenesis and ER stress-related proteins." (PMID 40564980, 2025). "The present study investigates the relationship between obesity, oxidative stress, and infertility through the expression of CART, leptin, and eNOS genes, focusing on the therapeutic potential of bariatric surgery in restoring reproductive health." (PMID 40002424, 2025). "The objective of the present study was to describe possible interactions of leptin, adiponectin, FTO rs9939609, and TMEM18 rs6548238 in children and adolescents with asthma, under the influence of obesity." (PMID 39159917, 2025). "Infants born to mothers with both T2D and obesity had significantly higher cord blood leptin than those exposed to only T2D in pregnancy (p = 0.012), and higher cord blood leptin than infants exposed to both GDM and obesity in pregnancy (p = 0.035)." (PMID 40045330, 2025). "Consistent with the literature, we observed significant hypertrophy in adipocytes from vWAT samples with obesity (Groups II and III) and an increase in LPS and inflammatory cytokines, including leptin and CCL2/MCP‐1." (PMID 40518865, 2025). "However, obesity‐induced leptin resistance may impair these protective effects." (PMID 40635334, 2025). "Chronic inflammation in obesity contributes to this condition, as TNF-α and the suppressor of cytokine signaling 3 (SOCS3) pathways impair leptin signaling in the hypothalamus." (PMID 40862455, 2025). "The existing literature to date paints a complex and often conflicting picture of the interplay between leptin, VEGF, MPO, CRP, and microvascular function in obesity." (PMID 40900465, 2025). "Thus, the serum adiponectin/leptin ratio may provide a more accurate and sensitive biomarker for assessing both adipocyte secretory function and the overall morphological status of adipose tissue, particularly under metabolic stress such as obesity." (PMID 41271970, 2025). "In addition, there is evidence suggesting that obesity is associated with lymph node metastases after RP, owing to the deranged prostatic microenvironment and cellular DNA caused by inflammatory factors (IL-6, IL-8, VEGF, leptin) and altered insulin-IGF-1 axis." (PMID 40364176, 2025). "While obesity and T2DM are complex and frequently polygenic diseases, leptin is a key regulator, and leptin resistance is a feature of these two metabolic diseases." (PMID 40125513, 2025). "This study further explored leptin signaling in ASCs, suggesting a potential mechanism for ASC dysfunction in the obesity-rich leptin environment of WAT." (PMID 39065712, 2024). "Among these proteins, leptin (LEP) levels were significantly overexpressed in both comparisons between MHO with NOH and comparison between obesity with NOH groups." (PMID 38548792, 2024). "Indeed, obesity, that is associated with hyperplasia of white adipose tissue, in addition to favouring a chronic inflammation, also causes hyperinsulinism, predisposes to T2DM, increases IGF-1 secretion, induces oxidative stress, and impairs leptin and adiponectin secretion." (PMID 37697017, 2024). "Similar results were found at the follow up visit for a subset (N = 80) of participants, and five proteins were elevated in the obesity group compared to NOH group, four of which (LEP, CSTB, FABP4 and SSCAD) were also identified in the baseline." (PMID 38548792, 2024). "In pregnant women, both obesity and diabetes increase pro-inflammatory cytokines and adipokines, such as TNF-α, IL-6, IL-1β, leptin, and resistin, which are involved in the inflammatory response." (PMID 39584800, 2024). "Finally, obesity may alter the PVN-SNS-ovary pathway through increasing leptin." (PMID 39963180, 2024). "We analyzed AT from individuals with obesity and age-matched lean counterparts for AT-EOS content, IL-4, circulating leptin levels, and measures of IR." (PMID 38206766, 2024).
Obesity (continued). "The authors identified four biomarkers (leptin, plasminogen activator inhibitor 1 (PAI1), alpha-1 acid glycoprotein 1 (AGP1), and CNTN1) for obesity and adiposity." (PMID 39408963, 2024). "Leptin (LEP), alternatively recognized as the obesity gene, influences food consumption, energy balance, and lipid metabolism." (PMID 42205494, 2024). "By restoring leptin sensitivity, PPB effectively reduced food intake, body weight, and fat accumulation, highlighting its therapeutic potential in managing obesity-related inflammation and metabolic dysfunction." (PMID 39682585, 2024). "Obesity leads to T-cell dysfunction and increases depletion of T cells with a PD-1-positive phenotype in the adipose tissue and TME through leptin production, whereas ICI therapy inhibits T cells by uncoupling PD-1/PD-L1 binding." (PMID 38267897, 2024). "Chronic gastric inflammation in patients with obesity is due to several factors like tumor necrosis factor-α (TNF-α), leptin, and adiponectin." (PMID 39124701, 2024). "Since tea polyphenols can improve leptin sensitivity by modulating obesity-related inflammatory processes and providing a weight-reducing effect, we suggest that white tea containing high levels of catechins and polyphenols may be effective in reducing serum leptin resistance." (PMID 39768256, 2024). "When adipocytes are enlarged due to obesity, the adipose tissue secretes inflammatory cytokines and chemokines such as tumor necrosis factor (TNF)-α, interleukin (IL)-6, and leptin, along with infiltration of immune cells, including macrophages." (PMID 38672461, 2024). "In these studies, we assessed the response to leptin 2 weeks after virus injection, which was before the time that the BNC2 LepR knockout mice developed obesity." (PMID 39478220, 2024). "Leptin expression and levels rise as obesity develops in DIO mice, and leptin administration has little (or no) effect to reverse obesity, suggesting “resistance” to endogenous and exogenous leptin." (PMID 38165042, 2024). "This study investigates the relationship between six obesity-related genes (CLOCK, FTO, GHRL, LEP, LEPR, MC4R) and their impact on BMI, WC, HC, WHR, and emotional eating behavior in 220 Romanian adults." (PMID 39203789, 2024). "Accordingly, in conditions with excess energy store or metabolic disturbance, as obesity and/or PCOS, leptin has an inhibitory effects on the gonads and induces H-P-O dysfunction." (PMID 38172476, 2024). "Our main objective was to evaluate the levels of adiponectin, leptin, TNFα, IL6, IGFs 1 and 2 in endometrial cancer patients compared to control patients and to examine their relationship with obesity." (PMID 38339282, 2024). "As expected, plasma leptin and LAR were significantly higher in children with obesity compared with those with normal weight." (PMID 38289144, 2024). "Semaglutide treatment restored GLP-1 levels, regulated Socs3 expression in ARC and improved leptin sensitivity and the hypothalamic anorexigenic signaling (POMC/MC4R) for obesity control in these obese mice." (PMID 39728000, 2024). "As expected in the leptin-resistance obesity model, the deficit in LEPR expression was counteracted by increased leptin expression." (PMID 38730110, 2024). "In participants with obesity, we observed significantly elevated inflammatory marker (TNF-α and IL-6), myeloperoxidase, leptin, and insulin levels (p < 0.05)." (PMID 39700087, 2024). "We found that leptin concentrations were different across GWG categories among adolescents with normal weight pBMI, but among adolescents living with overweight/obesity before pregnancy, the only difference was found when comparing adequate vs. excessive GWG." (PMID 38999894, 2024). "Of notice, with the development of obesity, obese mice modeling by 56 days of HFD respond to leptin for central administration (intracerebroventricularly) rather than peripheral administration (intraperitoneally or subcutaneously)." (PMID 38678254, 2024).
Obesity (continued). "Additionally, it has been shown that amylin could improve leptin sensitivity in obesity." (PMID 38338796, 2024). "The study will also assess thyroid hormones and leptin, angiopoietin like 8 (ANGPTL8), obesity, and cardiovascular diseases (CVD) in T2D patients." (PMID 39252284, 2024). "Mice with deletion of Gipr in Lepr cells were generated and metabolically characterized for alterations in diet-induced obesity (DIO), glucose control and leptin sensitivity." (PMID 38492844, 2024). "Leptin and ghrelin are important markers in PCOS due to their correlation with obesity, insulin resistance, and fertility." (PMID 39385878, 2024). "Overall, patients with obesity had higher leptin levels and lower EHRI, as expected, since leptin related inversely to EHRI and BMI." (PMID 39518373, 2024). "Considering that, in high concentrations, leptin is also a pro-inflammatory mediator, DGLA corroborates to a more pronounced state of inflammation in obesity." (PMID 39457561, 2024). "Moreover, obesity-related leptin resistance could occur in the hypothalamus, which was named central leptin resistance, while it could also happen in the adipose tissue, liver, and skeletal muscle, which was called peripheral leptin resistance." (PMID 38671836, 2024). "Thus, obesity may result from a general decrease in tissue sensitivity to leptin." (PMID 38541047, 2024). "Obesity induces a variety of systemic changes, including altered levels of insulin, insulin-like growth factor-1 (IGF-1), leptin, adiponectin, steroid hormones, and cytokines, creating an environment that favors tumor initiation and progression." (PMID 39630839, 2024). "Therefore, leptin-related signaling pathway may serve as a key mechanism linking sleep and obesity." (PMID 40302954, 2024). "EGCG’s mechanisms in the intervention of obesity have gradually come to be appreciated and include the regulation of the STAT1/SLC7A11 pathway, gut microbiota, leptin, and other mechanisms." (PMID 39539361, 2024). "In obesity-induced type 2 diabetes, pro-inflammatory molecules like IL-1β, IL-6, CCL2, CCL5, and leptin play key roles in the accumulation of MDSCs in adipose tissue." (PMID 39518420, 2024). "FIESLs demonstrated an anti-obesity effect against an HFD by regulating body weight, epididymal fat, blood glucose, leptin, and serum biomarkers such as total lipid, triglyceride, and total cholesterol, in addition to modulating gut microbiota composition." (PMID 38892626, 2024). "Studies have shown that chronic metabolic stress, such as obesity and HFD consumption, leads to chronic hyperactivity of AgRP neurons, which is likely a result of leptin resistance." (PMID 39916981, 2024). "Leptin also stimulates TRH and subsequently TSH secretion, thus contributing to mildly elevated TSH concentrations in subjects with obesity." (PMID 39203787, 2024). "Diet‐induced obesity model of the Fn1−/−ALB mouse showed normal weight gain and whole‐body fat mass, and normal adipose tissue depot volumes and unaltered circulating leptin and adiponectin levels." (PMID 39054559, 2024). "Insulin, leptin, the renin-angiotensin-aldosterone system (RAAS), sodium excretion, and stress natriuresis were some of the mechanisms by which obesity raised blood pressure." (PMID 38887608, 2024). "Adipokines such as leptin, adiponectin, and VEGF, along with pro-inflammatory cytokines, contribute to the inflammatory milieu and metabolic dysregulation observed in obesity." (PMID 39337290, 2024). "In fact, it has been suggested that, in obesity, elevated circulating GIP levels lead to the activation of EPAC/Raf1 signaling and this is an important condition for inducing neural leptin resistance." (PMID 39201336, 2024). "Next, considering the importance of adipokines in obesity and related metabolic syndromes, the gene expression of Adiponectin, HSL (hormone-sensitive lipase), and Leptin was evaluated." (PMID 39072314, 2024).